CTSS (cathepsin S)
Diseases named in the same sentence as CTSS in open-access papers (continued):
Sharing a sentence is not in itself a finding about the gene and the disease.
colorectal cancer (17 papers, 2011 to 2025). A primary or metastatic malignant neoplasm that affects the colon or rectum. "In cancer, elevated CTSS expression has been associated with poorer outcome in grade IV astrocytoma and colorectal carcinomas." (PMID 27097645, 2016). "Over the past 15 years, there has been an increasing body of evidence reporting increased expression of CTSS in a variety of malignancies, with this increased expression being associated with poorer prognosis in grade IV astrocytomas and colorectal carcinomas." (PMID 27097645, 2016). "Our analysis of colorectal cancer patient biopsies shows that cathepsin S associates with the cell membrane indicating a potential for ADCC targeting." (PMID 22168338, 2011). "The association of cathepsin S with colorectal cancer progression has been recently highlighted where it was shown to be a prognostic indicator." (PMID 22168338, 2011). "Among these enzymes, cathepsin S (CTSS), a cysteine protease, has been linked to tumor development and chemotherapy outcomes in colorectal cancer (CRC) patients." (PMID 40761244, 2025). "CTSS expression in cancer cells is crucial for the promotion of colorectal cancer growth and progression." (PMID 35494076, 2022). "The aim of this pilot retrospective study was to investigate the immunohistochemical expression of Cathepsin S (CatS) in three cohorts of colorectal cancer (CRC) patients (n=560)." (PMID 21989182, 2011). "To assess the effect of compound 6 on CTSS activity in a more complex milieu, we firstly incubated the inhibitor with murine MC38 colorectal carcinoma cell lysates, and measured turnover of a fluorogenic substrate Cbz-VVR-AMC." (PMID 27097645, 2016).
COVID-19 (16 papers, 2020 to 2025). A disease caused by infection with severe acute respiratory syndrome coronavirus 2. "The results showed that both the RNA editing (CTSS:chr1:150732177, and CTSS:chr1:150732184) and gene expression levels of CTSS significantly increased upon COVID-19 vaccination." (PMID 39308856, 2024). "Thus, the regulatory effect of S100A8 on CYBA and CTSS can be considered a characteristic of COVID-19 severity." (PMID 40362649, 2025). "Indeed, most recent proteomic analysis of COVID-19 autopsies suggested an overall upregulation of the cathepsin family members, including CTSB, CTSD, CTSE, CTSH, CTSK, CTSS, and CTSZ, in the lung of the COVID-19 patients." (PMID 34335974, 2021).
emphysema (15 papers, 2010 to 2025). "A previous study investigated the common functional polymorphisms (rs7534124, rs35989725, rs16827671, and rs34495036) in the 5′-flanking region in the CTSS promoter and found their possible association with pulmonary emphysema in the Japanese population." (PMID 29976774, 2018). "OR = 0.28) and the cathepsin S/cystatin C ratio (p = 0.002, OR = 0.82) were the strongest factors associated inversely with the presence of severe emphysema." (PMID 27994288, 2016). "Previous studies of animal models of emphysema have implicated cathepsin S in promoting airspace enlargement in mice." (PMID 27994288, 2016). "Studies of murine models of emphysema have implicated cathepsin S in promoting lung inflammation and destruction." (PMID 27994288, 2016). "Overexpression of IFN-γ in mice causes pulmonary emphysema, which is suggested to be due to cathepsin S-dependent epithelial cell apoptosis." (PMID 21067601, 2010). "Moreover, CTSS is implicated in pathogenesis of alveolar remodeling and pulmonary emphysema in interferon-γ-treated mouse." (PMID 29976774, 2018). "In addition, PU.1 has been shown to regulate expression and activity of emphysema-associated proteolytic enzymes such as cathepsin S and neutrophil elastase (NE)." (PMID 25962837, 2015). "It is also intriguing that plasma cathepsin S and cathepsin S/cystatin C ratios tend to be higher in patients with mild airflow limitation and emphysema than those in patients with severe impairment." (PMID 27994288, 2016). "Cathepsin S contributes to emphysema development in IFN-γ overexpressing transgenic mice by promoting epithelial cell apoptosis." (PMID 27994288, 2016). "Studies of transgenic mice that overexpress IL-13 and IFN-γ in an inducible- and lung-specific manner develop lung inflammation and emphysema due, in part, to increased lung levels of cysteine proteinases including cathepsin S." (PMID 27994288, 2016). "Moreover, Macro_SPP1 cells showed elevated expression of protease genes (e.g., ADAM9, CTSL, CTSS, and MMP9) in COPD, which were associated with emphysema and airway remodeling." (PMID 40589761, 2025). "Thus, the expression of factors associated with tissue destruction and healing, including MMP-12, MMP-9, and Cathepsin S, was also increased in emphysema mice." (PMID 32681029, 2020). "CTSS-deficient mice demonstrated protection against smoke-induced pathologies including pulmonary inflammation, airway hyperresponsiveness, emphysema, and lung function decline, while Protein Phosphatase 2A (PP2A) activation suppresses CTSS-driven pulmonary disorders." (PMID 40692794, 2025). "Moreover, patients with emphysema had increased serum CTSL and CTSS levels compared to patients lacking emphysema (P < 0.001 for CTSL, P = 0.0046 for CTSS)." (PMID 37816708, 2023). "Thus, plasma cathepsin S levels, but not cystatin C levels, were significantly increased in patients with AR and with mild COPD when compared with patients with severe airflow limitation and emphysema." (PMID 27994288, 2016).
systemic lupus erythematosus (13 papers, 2017 to 2025). An autoimmune multi-organ disease typically associated with vasculopathy and autoantibody production. "Another Roche compound, RO5461111, a competitive selective CTSS inhibitor, shows promise in systemic lupus erythematosus but awaits clinical entry." (PMID 40692794, 2025). "In lupus pathology, Blimp-1 suppresses CTSS expression and inhibits CTSS-mediated MHC-II activation in DCs, blocking antigen presentation to CD4+ follicular helper T cells." (PMID 40692794, 2025). "CTSS promotes systemic lupus erythematosus by regulating MHC class II-mediated T and B cell priming, germinal center formation and B cell maturation into plasma cells." (PMID 32398133, 2020). "Inhibition of CTSS in these models could reduce lupus progression and autoimmune-triggered inflammatory responses in macrophages." (PMID 32398133, 2020). "Furthermore, CTSS-overexpressing mice showed a marked increase in the production of IL-17, TNF-α, IFN-α and IFN-γ, which are known to be associated with lupus development, and the chemoattractants CCL2, CCL7 and CCLl12, which are activated by IFN-α to attract monocytes to inflammatory sites." (PMID 34381063, 2021). "The administration of a cathepsin S antagonist to MRL/lpr mice, a lupus-prone mouse, was demonstrated to suppress systemic autoimmunity and inflammation." (PMID 40002827, 2025). "In conclusion, overexpression of CTSS in mice influences TLR7 expression, autoantibodies and IFN-α, which leads to an autoimmune reaction and exacerbates lupus-like symptoms." (PMID 34381063, 2021).
oral cancer (12 papers, 2014 to 2025). "The injection of cathepsin S caused nociception in a mouse model while the injection of oral cancer cells in which the gene for cathepsin S is deleted generated less nociception." (PMID 34572924, 2021). "TNF-α has been linked to radioresistance of oral cancer cells whereas IFN-γ is able to induce cathepsin S expression which leads to radioresistance." (PMID 25005804, 2014). "Additionally, we looked at the possibility that cathepsin S overexpression causes oral cancer cells to migrate." (PMID 39159189, 2024). "We hypothesized that cathepsin S released by oral cancer and/or associated macrophages in the oral cancer microenvironment generates cancer pain through the activation of PAR2." (PMID 34572924, 2021). "Furthermore, the activation of the ERK/MAPK pathways is also involved in the regulation of LC3 and cathepsin S proteins and is potentially associated with cell autophagy and metastasis in oral cancer cells." (PMID 32397656, 2020). "Our findings demonstrate the crucial role that cathepsin S plays in the impact of pyrocurzerenone on oral cancer." (PMID 39159189, 2024). "Overexpression of cathepsin S increased cell migration and invasion, which was reversed in pyrocurzerenone‐treated oral cancer cells." (PMID 39159189, 2024). "The results reveal that cathepsin S induced migration and invasion in oral cancer cells, while pyrocurzerenone treatment reversed this effect." (PMID 39159189, 2024). "The orthotopic xenografts of human oral cancer cells also exhibited increased cathepsin S activity compared to naïve mouse tongue tissue." (PMID 34572924, 2021). "Genetic deletion of the gene for cathepsin S in a human oral cancer cell line reverses nociception in a mouse cancer model generated with the cancer cell line." (PMID 34572924, 2021). "We also demonstrated that cathepsin S activity is upregulated in immortalized human oral cancer cell lines compared to dysplastic oral keratinocytes." (PMID 34572924, 2021). "Cathepsin S, a lysosomal cysteine protease, is present and active in the oral cancer microenvironment." (PMID 34572924, 2021). "Our findings will lay the foundations for clinical trials of cathepsin S inhibitors for treating oral cancer pain." (PMID 34572924, 2021). "We also used ELISA to measure the intracellular and secreted cathepsin S in HSC-3 cells as well as a second human oral cancer line, OSC-20." (PMID 34572924, 2021). "More recently, cathepsin S has been shown to mediate autophagy and apoptosis in human oral cancer cell lines through p38 MAPK/JNK signaling pathways." (PMID 34572924, 2021). "Having demonstrated that purified recombinant cathepsin S can invoke facial nociception in vivo, we then investigated the ability of tumor cell-derived cathepsin S to provoke oral cancer pain." (PMID 34572924, 2021). "The multiplex immunolocalization of cathepsin S in human oral cancers suggests that carcinoma and macrophages generate cathepsin S in the oral cancer microenvironment." (PMID 34572924, 2021). "Collectively, our data provide evidence that sulforaphane inhibits human oral cancer cell migration by suppressing cathepsin S and the downstream target protein LC3." (PMID 29707130, 2018). "The ERK pathway and cathepsin S are both involved in oral cancer cells." (PMID 39159189, 2024). "This study showed that pyrocurzerenone reduced ERK1/2 expression of the proteins and cathepsin S, suggesting that it could be a valuable treatment to inhibit human oral cancer cell metastasis." (PMID 39159189, 2024). "Cathepsin S is a lysosomal cysteine protease that is involved in antigen presentation and contributes to diseases such as colitis, inflammation, and oral cancer." (PMID 38199506, 2024). "elucidated that sulforaphane, a natural phytochemical compound derived from cruciferous plants, could impede the migration of oral cancer cells by suppressing cathepsin S and LC3, suggesting a potential novel approach for the treatment of OSCC." (PMID 37334378, 2023).
oral cancer (continued). "In the oral cancer microenvironment, cathepsin S is both present and active, and when OSCC activates PAR2, it may contribute to oral cancer pain." (PMID 37334378, 2023). "We localized cathepsin S in macrophages and carcinoma cells in human oral cancers." (PMID 34572924, 2021). "We tested whether two human oral cancer cell lines produced nociception through cathepsin S. We generated separate groups of xenograft mice with HSC-3 and OSC-20." (PMID 34572924, 2021). "We undertook a series of experiments to define the role of cathepsin S in oral cancer pain." (PMID 34572924, 2021). "We compared cathepsin S activity in human oral cancer tumors versus patient-matched normal tissue; a human oral cancer cell line versus a benign dysplastic oral keratinocyte cell line; and in an orthotopic xenograft tongue cancer mouse model versus normal controls in mice." (PMID 34572924, 2021). "Cathepsin S, a lysosomal cysteine protease may play a role in oral cancer pain through a protease-activated receptor-2 (PAR2)-dependent mechanism." (PMID 34572924, 2021). "We demonstrated that cathepsin S is secreted by oral cancer cells, and that it cleaves human PAR2." (PMID 34572924, 2021). "We conclude that cathepsin S is responsible for oral cancer pain through PAR2 on neurons." (PMID 34572924, 2021). "We next investigated the ability of tumor-supplied cathepsin S to provoke oral cancer pain." (PMID 34572924, 2021). "Our results suggested that pyrocurzerenone decreased oral cancer cell migration and invasion ability by inhibiting ERK1/2 activation and cathepsin S expression." (PMID 39159189, 2024). "For instance, methyl protodioscin with cathepsin S interact through the JNK/p38 pathway, thereby enhancing oral cancer cell sensitivity to chemotherapeutics." (PMID 36352396, 2022). "In accordance with other cancers, we observed cathepsin S production by both keratin+ tumor cells and CD68+ macrophages of oral cancer specimens collected from four patients." (PMID 34572924, 2021). "Furthermore, purified cathepsin S was able to invoke facial nociception in vivo, also in an activity-dependent and PAR2-dependent manner, suggesting that cathepsin S would be capable of provoking oral cancer pain." (PMID 34572924, 2021). "Our findings suggest that cathepsin S and LC3 may be novel targets for oral cancer treatment." (PMID 29707130, 2018). "Thus, cathepsin S and LC3 may be new targets for oral cancer treatment." (PMID 29707130, 2018).
glioma (11 papers, 2014 to 2024). A benign or malignant brain and spinal cord tumor that arises from glial cells (astrocytes, oligodendrocytes, ependymal cells). "To confirm the role of CTSS in MEOX2 inducing glioma malignant phenotype, we constructed stable cell lines by transfected CTSS overexpression lentiviruses into shMEOX2 cells for the rescue assay." (PMID 35436995, 2022). "Then, CCK-8 and EdU assay results showed that silencing CTSS clearly inhibited the proliferation of glioma cells." (PMID 35436995, 2022). "In our study, depletion of CTSS in glioma cells or glioma stem cells suppressed cell proliferation or self-renewal, indicating CTSS also was a growth regulator in glioma." (PMID 35436995, 2022). "Wound-healing and transwell assay confirmed that silencing CTSS evidently inhibited glioma cells invasion and migration." (PMID 35436995, 2022). "Consistently, we analyzed CTSS expression and survival data of glioma patients from the public databases, and demonstrated that CTSS was upregulated and correlated with the poor prognosis." (PMID 35436995, 2022). "CCK-8 and EdU assay showed that rescue of CTSS partially restored the viability of MEOX2-silenced glioma cells, and limiting dilution assay revealed that rescue of CTSS also partially restored the self-renewal capacity of MEOX2-depleted GSC23 cells." (PMID 35436995, 2022). "Taken together, these data suggest that silencing CTSS inhibits cell proliferation, invasion, and migration of glioma." (PMID 35436995, 2022). "To identify the role of CTSS in aggressive behavior of glioma cells, we silenced the expression of CTSS in glioma cells by siRNA transfection." (PMID 35436995, 2022). "Our findings indicate that MEOX2 promotes tumorigenesis and progression of glioma partially through the regulation of CTSS." (PMID 35436995, 2022). "CTSS mRNA expression was significantly higher in low grade glioma (LGG) and GB samples than in normal samples according to TGCA data." (PMID 33425712, 2020). "Moreover, p-AKT (Ser473) and p-ERK1/2(Thr202/Tyr204) were decreased in CTSS knockdown cells, and it meant that AKT/ERK1/2 signaling axis was inactivated in CTSS-depleted glioma cells." (PMID 35436995, 2022). "In glioma, CTSS was overexpressed and identified as an independent prognostic factor." (PMID 35436995, 2022). "In our study, Cathepsin S (CTSS) was identified as a major downstream target gene of MEOX2 in glioma by RNA-sequencing, although, other target genes may be also regulated via MEOX2." (PMID 35436995, 2022). "Whether CTSS mediated glioma malignant phenotype by extracellular mechanism needs more profound exploration." (PMID 35436995, 2022). "Moreover, MEOX2-depleted induced inhibition of glioma cells migration and invasion were partially restored by re-expression of CTSS." (PMID 35436995, 2022). "Importantly, RNA-sequencing, ChIP-qPCR assay, and luciferase reporter assay revealed Cathepsin S (CTSS) as a novel transcriptional target of MEOX2 in glioma cells." (PMID 35436995, 2022). "Furthermore, some of these genes, such as MOBP and CTSS, have been confirmed to be related to glioma." (PMID 31138312, 2019). "Further, we found that CTSS, which is transcriptionally regulated by MEOX2, contributed to cell proliferation and motility in glioma." (PMID 35436995, 2022). "Together, these data confirmed that CTSS acts as a direct target gene of MEOX2 and is positively regulated by MEOX2 in glioma cells." (PMID 35436995, 2022). "Bioinformatics analysis of public databases results found upregulation of CTSS in glioma, especially in WHO 4 glioma, and glioma patients with high CTSS expression possessed poorer prognosis." (PMID 35436995, 2022). "Next, immunoblotting verified that silencing MEOX2 significantly suppressed CTSS protein expression, and overexpression of MEOX2 resulted in CTSS upregulation in glioma cells." (PMID 35436995, 2022). "We investigated the role of CTSS on the EMT process, focal adhesion and F-actin assembly in glioma cells." (PMID 35436995, 2022).
glioma (continued). "We analyzed the expression data of MEOX2 and CTSS in TCGA dataset, CTSS expression was found to be closely correlated with MEOX2 in glioma." (PMID 35436995, 2022). "Collectively, these data demonstrated that what the role of CTSS in aggressive behavior and its molecular mechanism in glioma cells is similar to MEOX2, also indicated that MEOX2 contributed to the malignant behavior of glioma by CTSS activation." (PMID 35436995, 2022). "The previous study has suggested that CTSS could mediate the process of invasion and migration in glioma, however, no reports have clearly confirmed the proliferation effect of CTSS on glioma cells." (PMID 35436995, 2022). "In addition, inhibition of MEOX2 impaired cell growth and motility in glioma, while CTSS expression rescue did not entirely restore behavior, implying the presence of other cellular or molecular mechanism." (PMID 35436995, 2022).
pancreatic cancer (11 papers, 2011 to 2025). "Cathepsin S also might contribute to visceral pain associated with gastrointestinal cancers including pancreatic cancer." (PMID 34572924, 2021). "Recently, a specific cathepsin inhibitor, ASPER-29, was found to suppress pancreatic cancer cell metastasis through dual inhibition of cathepsin-L and cathepsin-S." (PMID 39595046, 2024). "Cathepsin S is expressed on the surface of tumor cells representative of colorectal and pancreatic cancer (23%-79% positive expression)." (PMID 22168338, 2011). "However, CTSS and CTSE are overexpressed in prostate cancer and pancreatic cancer, respectively; this is contrary to the results of the present study and needs to be verified by more clinical and experimental studies in the future." (PMID 38883596, 2024).